PHKA2 (phosphorylase kinase regulatory subunit alpha 2)
Description:
Phosphorylase b kinase catalyzes the phosphorylation of serine in certain substrates, including troponin I. The alpha chain may bind calmodulin.
Synonyms: PYK; GSD9A; PHK; PYKL; XLG; XLG2
Tractability: Small molecule: a high-quality ligand is known. Antibody: UniProt places it where antibodies can reach, with high confidence; its Gene Ontology location is reachable by antibodies, with medium confidence. PROTAC: ubiquitination databases record sites on it; its protein half-life has been measured; a small molecule that binds it is known.
Target class: Kinase; Protein kinase regulatory subunit; Enzyme
Gene: Protein-coding gene on chromosome X (18,892,298 to 18,984,988, reverse strand). Ensembl gene ENSG00000044446.
Subcellular location: Cell membrane
Subcellular location (Human Protein Atlas): Nucleoplasm
Pathways (Reactome):
Metabolism: Glycogen breakdown (glycogenolysis)
Gene Ontology:
Molecular function: protein binding; phosphorylase kinase activity; calmodulin binding
Biological process: carbohydrate metabolic process; generation of precursor metabolites and energy; protein modification process; glycogen metabolic process
Cellular component: cytosol; phosphorylase kinase complex; cytoplasm; plasma membrane
Homologues: Orthologues: chimpanzee PHKA2 (99% identical), macaque PHKA2 (99% identical), dog PHKA2 (95% identical), pig PHKA2 (94% identical), rabbit PHKA2 (93% identical), guinea pig PHKA2 (93% identical), rat AABR07037995.1 (91% identical), mouse Phka2 (91% identical), tropical clawed frog phka1 (79% identical), zebrafish phka2 (73% identical), Drosophila melanogaster CG7766 (50% identical), Caenorhabditis elegans C14B9.8 (42% identical). Paralogues in human: PHKA1 (69% identical), PHKB (33% identical).
Diseases named in the same sentence as PHKA2 in open-access papers:
PHKA2 is named in the same sentence as 35 diseases in open-access papers, as found by Europe PMC text mining. Sharing a sentence is not in itself a finding about the gene and the disease. The quoted sentences say what the papers report.
glycogen storage disease (11 papers, 2011 to 2025). "Given the liver and muscle biopsy findings, a glycogen storage disease panel was sent which identified the patient to be hemizygous for a variant of uncertain significance denoted as p.Gly 131Val, c.392G > T in the PHKA2 gene." (PMID 33014498, 2020). "Liver phosphorylase b kinase (PhK) deficiency (glycogen storage disease type IX), one of the most common causes of glycogen storage disease, is brought by mutations in the PHKA2, PHKB and PHKG2 genes." (PMID 28410206, 2017). "The phosphorylase kinase PHKA2 has been implicated extensively in glycogen storage disease." (PMID 39794701, 2025). "We also identified a novel maternally inherited variant in PHKA2 (NM_000292.3: c.3374A > T (p.Glu1125Val)) that is associated with glycogen storage disease (GSD), type IXa1/2 (MIM 306000), characterized by phosphorylase kinase deficiency in the liver, leading to hepatomegaly and hypoglycemia." (PMID 33466780, 2021). "This study reported 12 Chinese patients with Glycogen storage disease and identified 18 gene variants of GAA, AGL, PHKA2 and PYGL (9 novel and 9 reported) by whole-exome sequencing." (PMID 36105079, 2022). "Search terms such as “glycogen storage disease type IXa,” “glycogen storage disease,” “PHKA2 gene,” “case report,” and “Asia” were used in various combinations and permutations across the databases." (PMID 31725618, 2019). "GSDIX is a group of glycogenoses caused by hepatic phosphorylase kinase deficiency, a hexadecameric enzyme comprising four copies each of four unique subunits encoded by four different genes; PHKA1, PHKA2, PHKB, and PHKG2." (PMID 34946936, 2021). "In humans, PHKA2 is responsible for glycogen storage diseases." (PMID 21831322, 2011). "A lack of the PHKA2 gene has been reported to cause glycogen storage disease." (PMID 37762634, 2023). "Imaging and liver biopsy findings suggested a hepatic glycogen storage disease (GSD) but not GSD type I. Genetic testing revealed a partial deletion of the PHKA2 gene, confirming the diagnosis of GSD type IXa." (PMID 40046366, 2025).
Hypoglycemia (7 papers, 2019 to 2025). A decreased concentration of glucose in the blood. "Glycogen storage disease type IXa (GSD IXa), caused by phosphorylase kinase mutations, primarily PHKA2, presents variably from mild hepatomegaly to severe liver dysfunction or isolated ketotic hypoglycemia." (PMID 40866742, 2025). "We report three patients with recurrent symptomatic ketotic hypoglycemia affected by PHKA2 variants of uncertain significance (VUS) and review the literature concerning GSD IXa, with a focus on our national case history." (PMID 40866742, 2025). "Given the persistence of unexplained hypoglycemia, an extensive next-generation sequencing (NGS) panel for hypoglycemia-related genes was subsequently performed which revealed a variant of uncertain significance in the PHKA2 gene." (PMID 40866742, 2025). "We report three patients with recurrent symptomatic ketotic hypoglycemia affected by PHKA2 variants of uncertain significance (VUS) and review the literature concerning GSD IXa." (PMID 40866742, 2025). "Mutations in PHKA2 gene cause glycogen storage disease type IXa, characterized by hypoglycemia, hepatomegaly, elevated liver enzymes, growth retardation and motor delay, hypercholesterolemia and hypertriglyceridemia." (PMID 33633136, 2021). "Recently, a cohort of patients with PHKA2 mutations was described as isolated ketotic hypoglycemia without hepatomegaly." (PMID 40866742, 2025). "More recently, isolated ketotic hypoglycemia without hepatomegaly has been related to PhK deficiency, mostly due to PHKA2 mutations." (PMID 35725468, 2022). "GSD III (AGL, MIM# 232400), VI (PYGL, MIM# 232700) and IXα (PHKA2, MIM# 306000) belong to hepatic GSD with basic features of hepatomegaly and hypoglycemia." (PMID 36105079, 2022).
glycogen storage disease type IXa (6 papers, 2019 to 2025). "GSD type IXa (GSD IXa) is associated with mutations in PHKA2 and transmitted as an X-recessive trait; it constitutes about 75% of total cases of GSD IX, the most frequent type of GSD, with a prevalence of 1:100,000." (PMID 40866742, 2025). "PHKA2 gene mutations can cause liver phosphorylase kinase (PhK) deficiency, resulting in glycogen storage disease type IXa (GSD IXa)." (PMID 30925902, 2019). "The clinical course and prognosis in this case are similar to those of glycogen storage disease type IXa, which is also caused by an abnormality of PHKA2." (PMID 31392108, 2019). "Up to now, more than 130 PHKA2 gene variants of GSD type IXa has been reported." (PMID 38192425, 2023). "We present the first case report of GSD type IXa in Northeast China caused by mutation of PHKA2." (PMID 31725618, 2019).
Glycogen storage disease type IX (5 papers, 2016 to 2025). "The aim of this study was to evaluate the PHKA2 mutation spectrum in Korean patients with GSD type IX." (PMID 27103379, 2016).
glioblastoma (2 papers, 2025). The most malignant astrocytic tumor (WHO grade IV). "SNORD113-3 enhances the expression of ADAR2, which promotes the editing of PHKA2 and subsequently regulates glucose and lipid metabolism as well as glioblastoma progression via the PHKA2/EBF1 axis." (PMID 41446042, 2025).
hepatocellular carcinoma (2 papers, 2016 to 2022). A malignant tumor that arises from hepatocytes. "However, the significance of HOMER1 and PHKA2 in glycolysis and in evaluating the prognosis of hepatocellular carcinoma patients remains unknown, and our current study suggested a possible role of them in glycolysis and HCC progression." (PMID 35924040, 2022).
liver fibrosis (2 papers, 2022 to 2025). "For instance, an evolution to liver fibrosis and chronic liver disease associated to PHKA2 mutations has been reported." (PMID 35725468, 2022).
glioma (1 paper, 2025). A benign or malignant brain and spinal cord tumor that arises from glial cells (astrocytes, oligodendrocytes, ependymal cells). "Compared with NBTs, glioma tissues showed significantly higher PHKA2 expression, positively correlating with pathological grades." (PMID 39794701, 2025).
renal tubular acidosis (1 paper, 2022). A group of genetic disorders of the kidney tubules characterized by the accumulation of metabolically produced acids with elevated plasma chloride, hyperchloremic metabolic acidosis. "Conversely, individuals affected by PHKA2 and PHKG2 mutations can display renal tubular acidosis and tubulopathy with secondary development of rickets in a patient with GSD type IXc." (PMID 35725468, 2022).
tumor (3 papers, 2024 to 2025). "SNORD113-3 and ADAR2 overexpression combined with PHKA2 knockdown had stronger tumor suppressive effects." (PMID 39794701, 2025). "Finally, in vivo studies using nude mice confirmed that SNORD113-3 and ADAR2 overexpression, along with PHKA2 knockdown, could suppress the formation of subcutaneous xenograft tumors and improve the outcome of tumor-bearing nude mice." (PMID 39794701, 2025). "PHKA2 was identified as an oncogenic factor, whereas SNORD113-3, ADAR2, and EBF1 acted as tumor suppressors." (PMID 39794701, 2025). "Finally, in vivo studies using nude mice confirmed that knockdown of PHKA2, along with overexpression of SNORD113-3 and ADAR2, could obviously suppress GBM subcutaneous xenograft tumor formation and improve the outcome of those tumor-bearing nude mice." (PMID 39794701, 2025).
genetic diseases (1 paper, 2025). "An interesting Korean pilot study performed a Rapid Targeted Sequencing trial, designed by a multidisciplinary team, on dry blood samples restricted exclusively to infants with suspected actionable genetic diseases, including the PHKA2 gene." (PMID 40428406, 2025).
PHKA2 also shares sentences with these, for which no sentence is quoted: psoriasis (4 papers); hepatic (2); liver cirrhosis (2); liver disease (2); mitochondrial disease (2); Babesia infection (1); Cirrhosis (1); developmental delay (1); diabetes (1); Hypercholesterolemia (1); hypertriglyceridemia (1); hypertrophic cardiomyopathy (1); infection (1); liver dysfunction (1); McArdle disease (1); mental disorder (1); muscular dystrophies (1); Myalgia (1); myopathies (1); Myotonia (1); phenylketonuria (1); rickets (1); Tarui disease (1); Turner syndrome (1).